APC (APC regulator of Wnt signaling pathway)
Diseases named in the same sentence as APC in open-access papers (continued):
Sharing a sentence is not in itself a finding about the gene and the disease.
Familial adenomatous polyposis (continued). "Desmoid-type fibromatosis is a condition characterized by benign, soft tissue tumors and is regarded as a form of familial adenomatous polyposis (FAP) caused by a germline mutation in the adenomatous polyposis coli (APC) gene." (PMID 29409537, 2018). "A Germline mutation of the APC gene and its inactivation has been found responsible for familial adenomatous polyposis (FAP)." (PMID 30115886, 2018). "Indeed, we have observed increased methylation in the promoters of several tumor suppressor genes including APC, a well-characterized tumor suppressor gene associated with familial adenomatous polyposis, and KLK10, which has been shown to repress proliferation and induce apoptosis in PCa cells." (PMID 29740534, 2018). "Another example for colon cancer involves inherited genetic variants in the APC gene that lead to familial adenomatous polyposis (FAP), affecting one in 10,000 individuals and conferring ∼95% risk of colorectal cancer by the age of 50." (PMID 29945886, 2018). "Patients with APC gene mutation develop hundreds to thousands of colorectal polyps at young age, of which the disease is termed familial adenomatous polyposis (FAP)." (PMID 30413188, 2018). "Germ-line mutations in the APC gene cause a hereditary cancer syndrome known as familial adenomatous polyposis (FAP)." (PMID 29652830, 2018). "Familial adenomatous polyposis (FAP) patients, in contrast, carry a heterozygous germline mutation in the APC gene, and only one hit is required for the complete loss of APC." (PMID 28426718, 2017). "BTPS type 2 refers to autosomal dominant inheritance of APC gene mutations with the development of Familial Adenomatous Polyposis (FAP), and the development of brain medulloblastomas." (PMID 28381238, 2017). "Germline APC alterations are the main cause of familial adenomatous polyposis (FAP) which confers 100% lifetime-risk of CRC if left untreated." (PMID 28769798, 2017). "Familial adenomatous polyposis (FAP) is an autosomal dominant precancerous condition which is associated with germline mutations of the APC gene." (PMID 28955048, 2017). "For example, sulindac significantly reduces the number of polyps in Familial Adenomatous Polyposis (FAP) patients who harbor a mutation in the APC gene and the use of aspirin is associated with a better clinical outcome in colon cancer patients." (PMID 28420162, 2017). "Notably, since APC is an endogenous inhibitor of tumorigenic β-catenin, the APC mutation leads to β-catenin stabilization, constitutive activation of Wnt signaling, and the consequent familial adenomatous polyposis (FAP) and sporadic colorectal cancer." (PMID 27769066, 2016). "Mutations to APC were first observed in colon tumours of FAP (familial adenomatous polyposis) patients in the 1990’s." (PMID 27196929, 2016). "Familial adenomatous polyposis (FAP) is a rare, inherited gastrointestinal (GI) disorder caused by a mutation in the Adenomatous Polyposis Coli (APC) tumor-suppressor gene, located on chromosome 5q21-22." (PMID 27480131, 2016). "Patients with familial adenomatous polyposis (FAP) inherit a germline mutation in one APC allele, and loss of the second allele leads to the development of polyps that will turn malignant if not removed." (PMID 28010732, 2016). "Germline mutations in this tumour suppressor gene (APC) give rise to familial adenomatous polyposis (FAP)." (PMID 28105931, 2016). "A minority have mutations of the adenomatous polyposis (APC) gene, which is associated with familial adenomatous polyposis (FAP)." (PMID 26686699, 2016). "Familial adenomatous polyposis (FAP) is an autosomal dominant hereditary colon cancer syndrome caused by mutations in adenomatous polyposis coli (APC) with both colonic and extra-colonic manifestations." (PMID 27777639, 2016).
Familial adenomatous polyposis (continued). "Individuals affected by familial adenomatous polyposis (FAP) carry a germline mutation in the APC gene ('first hit'), and show autosomal dominant inheritance with essentially 100 % penetrance (i.e., all will develop cancer)." (PMID 28010732, 2016). "Germline mutations in the tumor suppressor gene APC are associated with familial adenomatous polyposis (FAP)." (PMID 27217144, 2016). "Accordingly, hereditary mutations in one of the two APC alleles cause familial adenomatous polyposis (FAP) that is characterized by development of a large number of colorectal adenomas." (PMID 27589228, 2016). "Mutations of the human APC gene are found in most of familial adenomatous polyposis (FAP) patients, as well as in a majority of sporadic colorectal cancer cases." (PMID 27462415, 2015). "Patients with germline APC mutations develop familial adenomatous polyposis (FAP), which is marked by hundreds to thousands of adenomatous colon polyps and progression to invasive carcinomas." (PMID 24092877, 2014). "For example, patients with Familial Adenomatous Polyposis, caused by mutations in the APC gene, have a higher risk of developing desmoid tumors, but when a unselected cohort of this rare type of tumor is tested for APC mutations, only a small mutation detection rate has been found." (PMID 25937855, 2014). "The syndrome Familial Adenomatous Polyposis (FAP), associated with the development of hundreds to thousands of adenomatous polyps during teenage years, is due to dominant germ line mutations in the APC gene." (PMID 24416237, 2014). "Another inherited syndrome, which follows autosomal dominant inheritance, is familial adenomatous polyposis (FAP) and is characterized by germline mutations in APC gene." (PMID 24550697, 2014). "An example of these inherited syndromes is familial adenomatous polyposis (FAP), in which a mutation in one of the APC tumor suppressor gene alleles causes susceptibility to colorectal cancer." (PMID 24760231, 2014). "APC mutations occur in Familial Adenomatous Polyposis (FAP) and in 85% of sporadic colorectal cancers (CRC)." (PMID 23516639, 2013). "Constitutive activation of WNT/β-catenin signaling as a result of mutations in APC and β-catenin was first documented in both inherited familial adenomatous polyposis (FAP) and sporadic colon cancers." (PMID 22325146, 2012). "Mutations in the adenomatous polyposis coli (APC) gene is an early event in familial adenomatous polyposis (FAP), a syndrome in which there is an inherited predisposition to colon cancer." (PMID 21311763, 2011). "Germline loss-of-function mutations in the APC gene were originally identified to be associated with familial adenomatous polyposis (FAP), about 1% of which progress to CRC." (PMID 24212796, 2011). "Germ-line mutation of the APC gene causes familial adenomatous polyposis (FAP) and this, along with mice carrying similar mutations, has been investigated extensively as a paradigm for sporadic disease." (PMID 20628379, 2010). "In familial adenomatous polyposis (FAP) for example, different APC germline mutations lead to different spectra of extra-colonic manifestations depending on their localization along the gene and on the stability of the resulting truncated polypeptide." (PMID 19578404, 2009). "Especially from Familial Adenomatous Polyposis (FAP) and to a lesser extend Lynch Syndrome, which are caused by germline mutations in the APC and Mismatch Repair (MMR) genes, respectively." (PMID 19506731, 2008). "Germline mutations in the adenomatous polyposis gene (APC) result in familial adenomatous polyposis (FAP)." (PMID 17411426, 2007). "Overall, the causative APC mutation has been identified in only 30% of the patients with familial adenomatous polyposis (FAP) who have been included in studies reported in the literature." (PMID 7524601, 1994). "In a multicenter study in Japan, somatic APC mosaicism was identified in 9 (7.3%) of 123 cases of colorectal adenomatous polyposis." (PMID 41214301, 2026).
Familial adenomatous polyposis (continued). "Mutations in APC disrupt this process, causing β-catenin accumulation and leading to uncontrolled proliferation, a hallmark of CRC and familial adenomatous polyposis (FAP)." (PMID 40422048, 2025). "The polyposis, which includes familial adenomatous polyposis (FAP) and attenuated FAP (AFAP), is caused by pathogenic variants in the APC gene." (PMID 40807160, 2025). "In addition, less than 15% of AF cases occur in patients with adenomatous colonic polyposis (APC) gene mutations, including familial adenomatous polyposis (FAP) and tumor susceptibility syndrome." (PMID 41278299, 2025). "Familial Adenomatous Polyposis (FAP) is caused by pathogenic variants in APC or MUTYH (MAP)." (PMID 39859530, 2025). "Familial adenomatous polyposis (FAP) is a rare autosomal dominant syndrome with a prevalence of 1:8000–10,000 that is caused by germline inactivating mutations in the APC tumor suppressor gene (5q22.2)." (PMID 40111709, 2025). "Known risk factors for DF include APC and beta-catenin (CTNNB1) gene mutations, as in familial adenomatous polyposis, along with prior surgery, trauma, pregnancy, and oral contraceptive use." (PMID 41181483, 2025). "The main autosomal dominant adenomatous polyposis syndromes include familial adenomatous polyposis (FAP) and polymerase proofreading-associated polyposis (PPAP), caused by germline PVs in APC and the POLE and POLD1 genes, respectively." (PMID 40237887, 2025). "Conversely, monoallelic mutations in adenomatous polyposis coli (APC) cause familial adenomatous polyposis (FAP) and the brain tumour-polyposis syndrome, primarily medulloblastoma (79%), as an extracolonic manifestation of FAP." (PMID 40177144, 2025). "Familial adenomatous polyposis (FAP), an autosomal dominant inherited gastrointestinal tumor syndrome caused by a pathogenic germline mutation in the adenomatous polyposis coli (APC) gene, is characterized by the development of a multitude (100–1000) of colorectal adenomas." (PMID 40280932, 2025). "For instance, an edited APC mutant pig model of familial adenomatous polyposis (FAP) closely mimics human CRC in anatomy and tumor progression, facilitating evaluation of novel endoscopic diagnostics and minimally invasive surgical techniques." (PMID 41303362, 2025). "Familial adenomatous polyposis (FAP), responsible for about 1% of CRC cases, results from germline mutations in the APC gene." (PMID 40647462, 2025). "Individuals with congenital APC defects develop familial adenomatous polyposis (FAP), which progresses to CRC." (PMID 41303362, 2025). "APC was first discovered in 1991 for its involvement in familial adenomatous polyposis (FAP), which is an autosomal dominant inherited disorder characterized by the early onset of adenomatous polyps throughout the colon." (PMID 38562145, 2024). "Genetic analyses with mutant flies, a tumorigenic adenomatous polyposis coli-min (APCmin) mutant mice, and patients with familial adenomatous polyposis (FAP) allowed us to understand how the failure of β-catenin degradation by loss of function (LOF) of APC triggers colorectal cancer (CRC)." (PMID 38383910, 2024). "Additionally, cases of MCST in patients with familial adenomatous polyposis (FAP) with germline mutations in APC have been reported." (PMID 39588447, 2024). "APC mutations are thought to initiate events of colorectal carcinogenesis and are the major cause of the hereditary colon cancer syndrome known as Familial Adenomatous Polyposis (FAP)." (PMID 39605357, 2024). "Persons with familial adenomatous polyposis (FAP) carry germline APC mutations and develop tens to thousands of precancerous polyps at different stages and sizes, as well as occasional adenocarcinomas; these polyps are believed to represent early stages of CRC27,28." (PMID 39478119, 2024). "We also newly identified several SINE-R/VNTR/Alu (SVA) elements affecting the APC gene in two patients with familial adenomatous polyposis, as well as their sites of origin." (PMID 38368425, 2024).
Familial adenomatous polyposis (continued). "For instance, familial adenomatous polyposis (FAP), which causes thousands of polyps in the colon, is the end product of a germline mutation affecting the adenomatous polyposis coli (APC) gene with an autosomal dominant inheritance pattern." (PMID 39529755, 2024). "On the other hand, 5–10% of desmoid-type fibromatosis cases are hereditary and observed in individuals with familial adenomatous polyposis (FAP), which is characterized by a germline mutation in the adenomatous polyposis coli gene (APC)." (PMID 39410565, 2024). "NGS can identify gene mutations such as APC, SMAD4, and MSH2in patients with familial adenomatous polyposis [FAP], assisting in early detection and personalized risk assessment." (PMID 38999541, 2024). "Our analysis of APC mutations showed a prevalence of 13.43%, reinforcing the critical role this gene plays in FAP and attenuated familial adenomatous polyposis (AFAP)." (PMID 39674994, 2024). "Familial Adenomatous Polyposis (FAP) is inherited in an autosomal-dominant manner and results from germline mutations in the adenomatous polyposis (APC) gene, a tumor-suppressor gene that controls the Wnt/β-catenin signaling pathway." (PMID 37173923, 2023). "Approximately 8–10% of breast fibromatosis is a manifestation of Familial Adenomatous Polyposis (FAP), a syndromic mutation in Adenomatosis Polyposis Coli (APC gene)." (PMID 37232796, 2023). "Germline mutations in APC cause familial adenomatous polyposis (FAP)." (PMID 37117033, 2023). "To address this question, we employed a mouse model of human familial adenomatous polyposis known as the APC mutant line." (PMID 37325561, 2023). "Familial adenomatous polyposis (FAP) is a genetic condition whereby a fault in the adenomatous polyposis coli (APC) tumor suppressor gene leads to the formation of hundreds if not thousands of polyps in the colon." (PMID 38293318, 2023). "Familial adenomatous polyposis (FAP), which causes multiple adenomas in the intestines and induces small intestinal and colonic cancers in patients, develops due to APC mutation." (PMID 36739585, 2023). "Almost all intestinal adenomas from familial adenomatous polyposis (FAP) mouse lines that carry a truncation mutation at codon 580 in adenomatous polyposis coli (Apc580D) have both CTNNA1 and adenomatous polyposis coli (APC) gene deletions." (PMID 36741258, 2023). "Apc-based models are commonly used to study familial adenomatous polyposis (FAP), as this disease is driven via hereditary APC mutations." (PMID 37563222, 2023). "The APC locus was discovered through studying a rare hereditary syndrome, familial adenomatous polyposis (FAP)." (PMID 37927787, 2023). "APC gene mutations are a well-known pathogenic mutations of familial adenomatous polyposis (FAP)." (PMID 35586626, 2022). "Osteoma is rarely associated with Gardner syndrome (representing a phenotypic variant of familial adenomatous polyposis (FAP)), characterized by APC mutations and aberrant activation of WNT/β-catenin signaling." (PMID 34725446, 2022). "In particular, Patient P27, who carries an APC pathogenic variant, had a strong familial cancer history, in which her mother and sister were diagnosed with familial adenomatous polyposis (FAP), and her maternal grandmother and uncle, already dead, had colon cancer." (PMID 35495172, 2022). "Familial adenomatous polyposis (FAP), a well-studied disease with an autosomal dominant inheritance, has been reported to be caused by insertions and deletions in the adenomatous polyposis coli (APC) tumor suppressor gene." (PMID 35954375, 2022). "A prime example of this is an individual with X0/XY mosaicism who coincidentally also had familial adenomatous polyposis (FAP), a hereditary condition in which a heterozygous germline APC mutation leads to a heightened risk of colorectal cancer." (PMID 35415852, 2022).
Familial adenomatous polyposis (continued). "APC gene mutations were found in familial adenomatous polyposis (FAP) and 70%–80% of sporadic patients with CRC have APC gene inactivation." (PMID 35617032, 2022). "No considerations regarding fertility preservation, adenomatous polyposis coli (APC) gene status or history of familial adenomatous polyposis (FAP) were reported in the selected reports." (PMID 35919234, 2022). "Because APC mutations are almost universally the initiating event for polyps and CRCs, patients with familial adenomatous polyposis (FAP), who have germline mutations in APC, are a suitable population in which to study the natural progression of polyposis." (PMID 35726067, 2022). "Familial adenomatous polyposis (FAP) is an autosomal dominant disorder with a germline mutation in a tumor suppressor gene, Adenomatous Polyposis Coli (APC)." (PMID 35962368, 2022). "Familial adenomatous polyposis (FAP) is an autosomal dominant inherited condition associated with germline pathogenetic variants on the APC gene, characterized by the development of tens to thousands of adenomas in the large bowel starting from the second decade of life." (PMID 35053462, 2022). "The fraction of APC indels was significantly higher than that reported in patients with familial adenomatous polyposis (FAP) (p < 0.01) or in sporadic adenomas (p < 0.0001)." (PMID 34843512, 2021). "Also, germline mutation of the APC gene was described and is inherited in familial adenomatous polyposis (FAP) patients." (PMID 34150757, 2021). "While SPNs do not belong to any defined genetic syndrome, DTs have already been described in the context of familial adenomatous polyposis (FAP), and these are known to harbor germline mutations of APC." (PMID 33810291, 2021). "The APC Min mouse has phenotypic and genetic similarities to human familial adenomatous polyposis although the numerous adenomas that develop in the animal are mainly located in the small intestine." (PMID 34526999, 2021). "Familial adenomatous polyposis (FAP) is caused by pathogenic germline variants in the APC gene." (PMID 33740971, 2021). "Currently, mutations in 14 genes are suspected to underlie different subtypes of colorectal cancer, including mutations in the APC that increases predisposition to familial adenomatous polyposis (FAP) and defects in mismatch repair genes associated with Lynch Syndrome7." (PMID 33976257, 2021). "This research team then investigated the role of the gut microbiota in the development of familial adenomatous polyposis (FAP), which is an autosomal dominant disease caused by the APC gene in which many colorectal adenomas can develop." (PMID 32695120, 2020). "To investigate the mechanisms underlying the ability of APC mutations to drive CRC development in humans, we studied tissues from hereditary colon cancer patients from familial adenomatous polyposis (FAP) families." (PMID 33112876, 2020). "MUTYH germline mutations of BER (pathways 5,7,19) cause MUTYH-associated polyposis (MAP), a disorder similar to familial adenomatous polyposis (FAP), caused by mutations in the APC gene." (PMID 33121134, 2020). "Also, familial adenomatous polyposis (FAP) caused by germline mutations in the adenomatous polyposis coli (APC) gene, has been associated with an increased risk of developing BE." (PMID 32088803, 2020). "The index for familial adenomatous polyposis (FAP) is also a mutation in the APC gene." (PMID 33585000, 2020). "Furthermore, the common initiating mutation, APC, was discovered over 30 years ago by studying families with familial adenomatous polyposis (FAP)." (PMID 32325966, 2020).